MITF (melanocyte inducing transcription factor)
Diseases named in the same sentence as MITF in open-access papers (continued):
Sharing a sentence is not in itself a finding about the gene and the disease.
cancer (continued). "Similar to METTLs, MITF has long been recognized as a promoter of various types of cancer." (PMID 41114928, 2025). "The researchers propose that understanding MITF’s role in the immune system could lead to improved treatments for cancer and other diseases." (PMID 38351314, 2024). "This significant finding suggests that CDK4/6i treatment triggers the elevated expression of the MITF, which may potentially serve as a survival mechanism employed by cancer cells in response to CDK4/6 inhibition." (PMID 38961064, 2024). "Therefore, this review is focused on recent advances in elucidating novel functions of MITF in cancer progression and immune responses to cancer." (PMID 38351314, 2024). "FIR-preconditioned normal cells might promote a cellular self-defense system to evade transformed cancer cells via MITF-Akt-mTOR-exosome trajectory." (PMID 37123908, 2023). "Dysfunction of DDX3X leads to the selection of highly invasive MITF-low-expressing cancer cells." (PMID 35406721, 2022). "Nevertheless, targeting the MITF pathway shows promise as an anti-cancer approach." (PMID 35159049, 2022). "Therefore, we can expect that controlled pharmacological activation of MiTF/TFE proteins will recapitulate the pathological features of MiTF/TFE-driven cancer." (PMID 35665902, 2022). "These two subpopulations exhibited a slow cell cycle activity, a de-differentiated state and invasiveness, and were described by two different models, namely, the cancer stem cell (CSC) model and the microphthalmia-associated transcription factor (MITF)-rheostat phenotype switching model." (PMID 35631574, 2022). "However, TGF-β which can be secreted by cancer-associated fibroblasts can trigger a SMAD- and YAP/TEAD-driven transcriptional program, leading to a downregulation of MITF expression as well as its target genes." (PMID 34071193, 2021). "We therefore assumed that MITF would influence cancer progression through Hippo-YAP signaling axis." (PMID 34208068, 2021). "EDNRB and MITF also belong to the “pathways in cancer” pathway." (PMID 34722301, 2021). "Second, we used the Cancer Genome Atlas dataset to characterize differential gene expression and split the tumors into two groups: the tumors with the 10% highest (MITFhigh) and 10% lowest (MITFlow) expression of MITF." (PMID 33438577, 2021). "Increased LINC00518 expression may be induced by MITF, a melanocyte-specific TF, and promote cancer-related processes, such as cell proliferation and migration." (PMID 33371395, 2020). "WVBF could up-regulate Fas, c-EBPβ, sphingosine kinase-1 (Sphkl), TGF-β, MITF, down-regulated IL-1R, and synergistically lead to anti-inflammatory and anti-cancer effect." (PMID 31214025, 2019). "Using datasets available at the cancer genome atlas (TCGA), we found that the gene encoding the endolysosomal cation channel, TRPML1 (MCOLN1), was upregulated in oncogenic HRAS-expressing tumors due to the combined actions of MiTF and TFEB." (PMID 31526156, 2019). "We examined also the pattern of cancer SC markers after MITF down‐regulation." (PMID 29369499, 2018). "It is important to highlight that the tissue-specific differences in MITF expression among different cancer types suggest that in order to fully comprehend MITF’s role in cancer, its expression and function has to be analyzed in the context of each particular cell and tissue type." (PMID 30310055, 2018). "Our findings may also impact the understanding and treatment of melanoma, as the Sox10 target MITF is a lineage oncogene in this neural crest-derived cancer." (PMID 28832322, 2017). "According to these findings, it was hypothesized that a key event in cancer stem cell maintenance could consist of the events that maintain low MITF levels in these cells." (PMID 29156643, 2017). "In particular, we predict isoform switches that affect the encoded protein for the cancer drivers CCND3, MYH11, MITF, RALGD5, ABI1, PRDM1 and PPARG, which may have implications for targeted therapy development." (PMID 25578962, 2015).
cancer (continued). "Two other pathways that are significantly upregulated in UM with low MITF are KRAS_SIGNALING_UP and MTORC1_SIGNALING: these are not pathways that are commonly associated with UM but both play a role in other types of cancer and specifically in metabolic reprogramming." (PMID 37240204, 2023). "Thus, YAP/Hippo signaling may promote the progression of TNBC, which makes MITF/YAP inhibition a target of much interest for cancer prevention and treatment." (PMID 36045272, 2022). "The results uncover a hierarchical cascade whereby microenvironmental stresses, including glucose limitation, lead MITF, TFEB, and TFE3 to drive distinct biologically important transcription programs that underpin phenotypic transitions in cancer." (PMID 41275493, 2025). "Importantly, in the context of β-glucan therapies, pharmacological MITF inhibition could prevent trained inflammatory osteoclastogenesis without in principle interfering with the intended beneficial effects (e.g., actions against infections or cancer)." (PMID 40020679, 2025). "A further interesting function of MITF is its interaction with pseudo-EMT, which is involved in pathological processes such as cancer." (PMID 35682684, 2022). "In order to further confirm that the observed anti-cancer effects of ACY-1215 result from the regulation of MITF, OMM2.5 cells were treated with a MITF pathway inhibitor, ML329, in vitro and in vivo in zebrafish OMM2.5 xenografts." (PMID 35159049, 2022). "SOX5 also regulates a variety of targets in cancers, including EZH2, twist 1, P2RY8, MITF, and others." (PMID 35880568, 2022). "Surprisingly, BCL2L1, E2F1, HRAS, MAPK8, MITF, RELA, and SP1 were all found in the mitophagy and cancer pathways." (PMID 34262589, 2021). "The MiT/TFE family of transcription factors (MITF, TFE3, and TFEB), which control transcriptional programs for autophagy and lysosome biogenesis have emerged as regulators of energy metabolism in cancer." (PMID 32397616, 2020). "For example, ASCL1, CDX2, IRF4, MITF, NKX2-1, PAX8 and SOX2 were pinpointed as outliers in cell lines of their corresponding cancer tissue origins." (PMID 31050342, 2019). "To further validate our findings, we probed the correlation of MITF and CDK2 in the publicly available Cancer Cell Line Encyclopedia (CCLE) containing 935 cell lines." (PMID 29507054, 2018). "We also analyzed a panel of putative cancer-related genes, including CDK8, MITF, SMAD7, KLF12, AG02, CDK14, and BCL-9, but only PTEN expression was shown to be significantly altered by miR-216a overexpression." (PMID 30061175, 2018). "In the end, definitive diagnosis was made due to the fast-growing and widely disseminated nature of the cancer, positive staining with MART-1 and MITF, and FISH analysis revealing normal EWS gene." (PMID 24274261, 2013). "Two of the last hub genes, MITF and STAT1 are involved in human cancers." (PMID 39820173, 2025). "Six of these PGVs were in cancer predisposition genes (ATR, CHEK2 (3x), SDHA and MITF) without an established association with familial glioblastoma." (PMID 41168197, 2025). "To better elucidate the induction of EMT by INHBA in PanNENs, we defined 17 upregulated transcription factors in INHBA-overexpressed PanNEN cells and further analyses identified MITF as a regulator of EMT downstream of INHBA, which has been demonstrated in various aggressive cancers." (PMID 38252148, 2024).
cancer (continued). "Activation of TFE3, a member of the MiTF/TFE family of transcription factors that regulate energy metabolism and cancer survival may also induce protective autophagy." (PMID 37180606, 2023). "Next, we expanded our analysis to a second cancer type, SKCM, and examined whether BayesPrism would recover expression differences characteristic of the AXL and MITF malignant cell states." (PMID 35469013, 2022). "Notably, BCL2L1, E2F1, HRAS, MAPK8, MITF, RELA, and SP1 were found in both mitophagy and cancer pathways." (PMID 34262589, 2021). "The top amplified cancer genes were KRAS, CDK4, BRAF, IL6, TLK2 and MITF." (PMID 34313788, 2021). "Although not related to the cancer field, this model can provide robust insights into how MITF functions in immunity." (PMID 33276788, 2020). "For instance, while MITF, SPDEF, CNOT7, BTK, PAF1, and PAX5 seem to be novel key regulators in the context of HPV-induced carcinogenesis, they are apparently already known to play essential roles in other cancer entities." (PMID 30918060, 2019). "We identified potential novel upstream regulators (e.g., CNOT7, SPDEF, MITF, and PAX5) controlling distinct clusters of genes within the HPV-host cell network as well as distinct factors (e.g., CPPED1, LCP1, and TAGLN) with essential functions in cancer." (PMID 30918060, 2019). "Thus, Myc/Max and other bHLH transcription factors likely influence the effects of TFEB, MiTF and TFE3 to drive endolysosomal biogenesis in certain cancers." (PMID 31526156, 2019). "The roles of MEF2A and MITF have not been previously characterized in these cancers and may present promising targets for study and potentially for therapeutic intervention." (PMID 31554806, 2019). "Four transcription factors, EGR1, HNF4A, MITF and FOXA2, appeared to form a hub of upstream regulators in all five gene-sets (p < 0.001) and could explain the apparent overlap in disease outcomes (ie. cancer)." (PMID 28531178, 2017). "Our analysis suggests that whereas gene level expression estimates of TPM4 and MITF contribute little to the discrimination of cancer cell lines from non-oncogenic cells, expression estimates specific to one or more isoforms of these genes have a better discriminating power." (PMID 23594586, 2013). "In the Cancer Cell Line Encyclopedia (CCLE), expression of FNIP2 and RRAGD, and to some extent RRAGC, but not RRAGA or RRAGB, correlates with MITF expression." (PMID 41275493, 2025). "Endosome acidification, MITF-dependent lysosome biogenesis, and ESCRT proteins Hrs and Vps4 are all required for Wnt/β-catenin activation, but the role of late endosome-dependent Wnt activation in cancer pathogenesis has not been well defined." (PMID 34035258, 2021). "MITF, which is not expressed in NB cells, has been shown to have a role in the regulation of melanocyte development and is similar to MYCN in that it is a reported oncogene which is amplified in cancer." (PMID 19997598, 2009).
infection (9 papers, 2010 to 2024). The state of being infected such as from the introduction of a foreign agent such as serum, vaccine, antigenic substance or organism. "MITF regulates several genes in response to infection by some pathogens, such as Vibrio parahaemolyticus, and is related to activation of B lymphocytes in L. longipalpis infection." (PMID 36356085, 2022). "MitF (LegG1) activates the host small GTPase Ran to promote mitochondrial fragmentation during infection of human macrophages." (PMID 34882089, 2021). "Similar results were observed following infection with lentiviral vectors expressing two different shRNAs directed against BPTF both of which led to diminished BPTF levels whereas MITF expression was unaffected." (PMID 26440048, 2015). "Infection of either primary human or melan-Ink4a-Arf1 melanocytes with shATF2 markedly increased MITF transcription and protein expression." (PMID 21203491, 2010). "Our results suggest that dysregulation of MITF in macrophages worsens infection severity in patients, but the mechanism behind this is not understood especially with the current evidence of macrophage-related inflammation in COVID-19 infections." (PMID 33923155, 2021). "However, the expression of Pkd2, Pkhd1, Kif12, Cadherin16 and Socs3, which are known as HNF-1β target genes, did not change (data not shown), and only a few genes, including NR1H4, MITF, SLC3A1, and SLCO4C1, were significantly upregulated 9 h after Ad-HNF1B infection." (PMID 27196561, 2016).
neurodegenerative disease (4 papers, 2022 to 2024). A disorder of the central nervous system characterized by gradual and progressive loss of neural tissue and neurologic function. "The dysregulation of MiTF/TFE proteins was shown to be involved in the development and progression of neurodegenerative diseases." (PMID 35665902, 2022). "Finally, the activation of MiTF/TFE transcription factors, particularly of TFEB, can promote the clearance of intracellular waste in both LSDs and more common neurodegenerative diseases." (PMID 35665902, 2022).
gastrointestinal tumors (2 papers, 2019 to 2023). "Since the microphthalmia factor (MITF) has been described as regulating KIT expression (mainly in murine MCs and human gastrointestinal tumors), we finally compared CREB to MITF." (PMID 38201246, 2023).
hematologic malignancies (2 papers, 2019 to 2025). "Incidental findings of P/LP germline variants in genes associated with non-hematologic malignancies were seen in seven patients, including heterozygous MUTYH G396D identified in four patients, MITF E419K in two, and a CDH1 loss-of-function in one patient." (PMID 39975890, 2025).
kidney disease (2 papers, 2017 to 2024). "The other members of the TFEB family (TFE3, MITF, and TFEC) may impact TSC-associated kidney disease and other manifestations of TSC, via similar mechanisms." (PMID 38195686, 2024).
cardiovascular disease (1 paper, 2016). "The eight significant SNPs identified in Model 1 are located in five genes —LRP8, CAPN13, MITF, SGCD and MLL3—previously implicated in BP variation or cardiovascular disease." (PMID 28002425, 2016).
skin disorder (1 paper, 2023). Any deviation from the normal structure or function of the skin or subcutaneous tissue that is manifested by a characteristic set of symptoms and signs. "In conclusion, CAFB is a promising ingredient for treating skin disorders caused by the overproduction of melanin and its underlying mechanisms involving the modulation of tyrosinase, mainly mediated by the regulation of the cAMP cascade and MITF pathway." (PMID 37408224, 2023).
MITF also shares sentences with these, for which no sentence is quoted: coloboma (5 papers); Hirschsprung disease (4); colorectal cancer (3); eye melanomas (3); Hearing impairment (3); lymphoma (3); mesothelioma (3); Peripheral demyelinating neuropathy (3); pheochromocytoma (3); 22q11.2 deletion syndrome (2); acute myeloid leukemia (2); alveolar soft part sarcoma (2); cardiomyopathy (2); CHARGE syndrome (2); coloboma, osteopetrosis, microphthalmia, macrocephaly, albinism, and deafness (2); esophageal squamous cell carcinoma (2); hereditary cancer (2); Kallmann syndrome (2); LEOPARD syndrome (2); lymphangioleiomyomatosis (2); metabolic disorders (2); Obesity (2); ovarian cancer (2); renal neoplasia (2); spindle cell neoplasm (2); viral infection (2); acral melanomas (1); adenovirus infection (1); Adult onset (1); Aganglionic megacolon (1).
A further 104 diseases each share a sentence with MITF in 1 paper.